LINC00702 (long independently transcribed non-coding RNA 702)
Gene: Long non-coding RNA gene on chromosome 10 (4,201,141 to 4,268,709, reverse strand). Ensembl gene ENSG00000233117.
Diseases named in the same sentence as LINC00702 in open-access papers:
LINC00702 is named in the same sentence as 9 diseases in open-access papers, as found by Europe PMC text mining. Sharing a sentence is not in itself a finding about the gene and the disease. The quoted sentences say what the papers report.
colorectal cancer (2 papers, 2022). A primary or metastatic malignant neoplasm that affects the colon or rectum. "LINC00702 functions as a tumor-suppressor gene by promoting PTEN expression in colorectal cancer and nonsmall cell lung cancer (NSCLC) while as an oncogene in malignant meningioma and ovarian cancer." (PMID 35846431, 2022). "On the other hand, LINC00702 was found downregulated in colorectal cancer and repressed tumor cell proliferation, invasion, and migration through suppressing the PI3K/AKT pathway by promoting PTEN expression." (PMID 36566321, 2022).
bladder cancer (1 paper, 2023). "Thus, LINC00702-activated DUSP1 suppresses bladder cancer cell proliferation and inhibits the secretion of inflammatory cytokines IL-4, IL-10, and TNF-α M2-OAM in bladder cancer." (PMID 38139370, 2023).
lymph node metastasis (1 paper, 2019). "Additionally, the outcome of spearman correlation test and multivariate cox regression analysis confirmed the level of LINC00702 was negatively correlated with tumor size, lymph node metastasis and distant metastasis in patients with NSCLC." (PMID 30840927, 2019).
meningioma (1 paper, 2021). A generally slow growing tumor attached to the dura mater. "Meanwhile, SNHG1, LINC00702, LINC00460, and MEG3 have been found to partake in the pathogenesis of meningioma." (PMID 34885097, 2021).
tumor (7 papers, 2019 to 2025). "RT–qPCR results showed that LINC00924, LINC00944, and LINC00865 were highly expressed in tumour tissues, while LINC00702 and ZFAS1 were expressed at low levels in tumour tissues." (PMID 36936957, 2023). "LINC00702 was found to be related to tumour size and tumour metastasis and was significantly downregulated in NSCLC patients." (PMID 36936957, 2023). "Collectively, LINC00702 may play a dual role in cancer pathogenesis acting as a tumor suppressor or tumor-promoting factor, which is attributed to the heterogeneity of tumors." (PMID 39345881, 2024). "The role of LINC00702 in tumor development has been studied in several researches." (PMID 35846431, 2022). "LINC00702, C8orf88, and FILP1, upregulated in diffuse-type GC, promoted tumor progression and metastasis through immune suppression and activation of tumor-promoting pathways." (PMID 40777025, 2025). "The expression of LINC02257, LINC02188, MYOSLID, C6orf223, MYG1-AS1, and Lnc-SKA2-1 was upregulated in tumor samples, while the expression of LINC00702, LOC100129434, and LINC01915 was downregulated in tumor samples." (PMID 35846431, 2022). "LINC00702, AC121247.2, HSD11B1-AS1, NR4A1AS, AC011472.4, LIPE-AS1, etc., were lower expressed in tumor tissues, conversely, AP001434.1, LINC02257, LINC01655, LINC01614, AF015262.1, LMNTD2-AS1, etc., were highly expressed in tumor tissues." (PMID 34671639, 2021).
LINC00702 also shares sentences with these, for which no sentence is quoted: cancer (2 papers); malignant meningioma (1); nonsmall cell lung cancer (1); ovarian carcinoma (1).